MIR371A (microRNA 371a)
Synonyms: hsa-mir-371; MIR371; MIRN371; hsa-mir-371a
Gene: MicroRNA gene on chromosome 19 (53,787,675 to 53,787,741, forward strand). Ensembl gene ENSG00000199031.
Gene Ontology:
Biological process: miRNA-mediated post-transcriptional gene silencing
Homologues: Orthologues: chimpanzee ptr-mir-371 (100% identical), macaque mml-mir-371 (90% identical), pig ssc-mir-371 (84% identical), rabbit MIR371A (76% identical), mouse Mir292 (70% identical), guinea pig MIR371A (67% identical), mouse Mir293 (66% identical). Paralogues in human: MIR372 (73% identical).
Diseases named in the same sentence as MIR371A in open-access papers:
MIR371A is named in the same sentence as 9 diseases in open-access papers, as found by Europe PMC text mining. Sharing a sentence is not in itself a finding about the gene and the disease.
MIR371A shares sentences with these, for which no sentence is quoted: tumor (2 papers); breast carcinoma (1); esophageal cancer (1); gastric adenocarcinoma (1); germ cell tumor (1); lung carcinoma (1); parathyroid carcinomas (1); retinoblastoma (1); Thyroid adenoma (1).